MMP8 (matrix metallopeptidase 8)
Diseases named in the same sentence as MMP8 in open-access papers (continued):
Sharing a sentence is not in itself a finding about the gene and the disease.
lung fibrosis (continued). "Aside from serine proteases, neutrophils are an important source of matrix metallopeptidases (MMPs), such as MMP-2, MMP-8, and MMP-9, which are involved in pulmonary fibrosis." (PMID 32630825, 2020). "MMP-8 reduces lung levels of MIP-1α and IP-10 in bleomycin-treated mice to promote pulmonary fibrosis." (PMID 24828408, 2014). "Furthermore, ELISA was used to detect pulmonary fibrosis markers COL-1, COL-3, WNT, Vimentin, β-Catenin, Fibronectin, α-SMA, N-Cadherin, E-Cadherin, TWIST, CTGF, FGF2, PDGF-α, MMP2, MMP8, MMP9, MMP13, TIMP1, TGF-β, Smad2, and Smad3 expression levels." (PMID 37812357, 2023). "Mice lacking MMP8 are protected from bleomycin-induced pulmonary fibrosis and their fibroblasts show higher IL-10 levels and lower collagen synthesis, compared to those of wild type mice." (PMID 34072833, 2021). "Thus, surface‐bound MMP‐8 on LPS‐activated monocytes and macrophages could be targeted therapeutically to decrease macrophage tissue infiltration in diseases in which macrophages promote disease progression including idiopathic pulmonary fibrosis and hepatic cirrhosis." (PMID 33656791, 2021). "This property could have important value for lung disorders, such as chronic obstructive pulmonary disease (COPD) and idiopathic pulmonary fibrosis (IPF), where MMP-8 inhibition has shown to be beneficial." (PMID 32784891, 2020). "Depletion of neutrophils might attenuate lung fibrosis and inflammation through down-regulating TGF-β1, TNF-α, IL-17, MMP-8 and TIMP-2." (PMID 27690127, 2016). "Although prior studies reported that MMP-8 levels are increased in plasma and bronchoalveolar lavage fluid (BALF) samples from IPF patients, neither the bioactive forms nor the cellular sources of MMP-8 in idiopathic pulmonary fibrosis (IPF) patients have been identified." (PMID 24828408, 2014). "Therefore, we hypothesized that mice lacking MMP-8 would develop less lung fibrosis than their respective wildtype counterparts." (PMID 20949050, 2010). "Additional collagenases may exert a major role in lung homeostasis, possibly MMP-8 and MMP-13, which are also found to be induced in chronic obstructive pulmonary disease, or MMP-1, which is absent in fibroblast foci from idiopathic pulmonary fibrosis." (PMID 27066886, 2016).
melanoma (24 papers, 2011 to 2025). A malignant, usually aggressive tumor composed of atypical, neoplastic melanocytes. "Functional analysis of the identified mutations verified that all mutations result in loss-of-function of MMP8, contributing to melanoma progression." (PMID 38659022, 2024). "For example, mutations in the MMP8 gene, often found in melanoma, enhance the migration of immortalised transformed human Mel-STR melanocytes in vitro and in vivo." (PMID 33204027, 2021). "Particularly in melanoma; MMP-8 is frequently mutated by loss of heterozygosity (LOH), which is a hallmark for tumour-suppressor proteins." (PMID 28330493, 2017). "Subsequently, MMP8 KO mice were also shown to be susceptible to melanoma." (PMID 31514474, 2019). "An increased risk of malignant melanoma is correlated with the expression of MMP-8." (PMID 27271600, 2016). "In melanoma and lung cancer cell lines, increased expression of MMP8 (matrix metalloproteinase 8) prevents metastasis formation through the modulation of tumor cell adhesion and invasion." (PMID 39858031, 2025). "It is noteworthy that MMP-8, previously thought to be present only in neutrophils, has been later demonstrated to be expressed in various cancers such melanoma and head-and-neck carcinoma." (PMID 36713871, 2022). "For example, a higher MMP-8 was found in the serum of melanoma patients with highly vascularized primary tumors, suggesting a pro-tumorigenic function." (PMID 35267541, 2022). "MMP8 was also upregulated in the secretome of DNA-dependent protein kinase, catalytic subunit (DNA-PKcs)-silenced melanoma cells that metastasized less in vivo and migrated/invaded less in vitro, providing indirect evidence for the protective role of MMP8." (PMID 31514474, 2019). "A similar protective role for host neutrophil-derived MMP-8 was observed in spontaneous and experimental metastasis experiments with syngeneic Lewis lung carcinoma and B16F10 melanoma cells in C57Bl6 Mmp8-null mice." (PMID 25848906, 2015). "Enhanced expression of MMP-8 by melanoma cells was found to decrease their invasion and migration by enhancing their adhesion to the ECM." (PMID 25848906, 2015). "The protective role of MMP-8 against melanoma development was reinforced in a study showing that MMP-8 is frequently mutated in melanoma." (PMID 24788523, 2014). "While some studies show the relationship between MMP-8 and tumor progression, there are others associating MMP-8 with tumor suppression, especially in melanoma." (PMID 24788523, 2014). "Arazyme treatment or immunization induced the production of protease-specific IgG that cross-reacted with melanoma MMP-8." (PMID 24788523, 2014). "Experiments using MMP-8 genetically deficient mice showed the increased incidence of skin cancer, and overexpression of MMP-8 in melanoma cells decreased tumor invasion and up regulated the adhesion of tumor cells to ECM." (PMID 24788523, 2014). "Additionally, arazyme stimulated the production of protease-specific IgG that can cross-react with MMP-8 from melanoma cells, thereby inhibiting the in vivo metastatic process." (PMID 41019059, 2025). "However, MMP-8 (a collagenase II enzyme) has anti-tumor and anti-metastatic activity in cancers such as melanoma." (PMID 34207884, 2021). "Low serum MMP8 levels in melanoma patients correlated with better overall survival." (PMID 31514474, 2019). "A higher level of MMP8 in the epidermal-dermal border correlates with melanoma invasiveness." (PMID 31514474, 2019). "Therefore, the wild type-proteolytic active MMP-8 displays tumor suppressive effects due to inhibition of tumor migration, invasion and metastasis, whereas mutant MMP-8 is inactive, allowing melanoma progression." (PMID 24788523, 2014). "In human melanoma, function-inactivating mutations in MMP8 have been found at high frequency, and wild-type but not mutant forms suppressed tumor formation in soft agar assays, supporting its role as a tumor suppressor." (PMID 23632023, 2013).
melanoma (continued). "Reports have shown that MMP8, which has a strong correlation with the development of skin cancers, particularly breast, melanoma, and tongue, could diminish or accelerate cancer progression via its breaking down of the ECM and cleavage of cell adhesion proteins." (PMID 37359526, 2023). "Murine melanoma cells, B16F10, formed more lung metastases in MMP8 KO mice, whereas the overexpression of MMP8 in tumor cells lowered the number and size of metastases." (PMID 31514474, 2019). "Another possibility is the over-expression of soluble molecules that inhibit or decrease metastasis in melanoma, including PF4/CXCL4, TR47, and MMP8, which could be used in combination with CAR T cells that target surface molecules." (PMID 34207884, 2021). "Because MMP3 activates the collagenases MMP1, MMP8 and MMP13 that are capable of degrading collagen types I, II, III, V and IX as well as native fibrillary collagen which is crucial for melanoma metastasis, we tested for MMP3 secretion by performing western blot analyses." (PMID 31728131, 2019). "In vitro studies on skin cancer revealed that most melanoma cell lines, but not normal melanocytes, express MMP8 mRNA." (PMID 31514474, 2019). "Collagenases, MMP-1, MMP-8, and MMP-13, are the dominant extracellular proteinases with the ability to cleave native fibrillar collagen types I, II, III, and V. As they can degrade dermal collagen, they are particularly relevant in melanoma." (PMID 27271600, 2016).
colorectal cancer (19 papers, 2012 to 2026). A primary or metastatic malignant neoplasm that affects the colon or rectum. "When liver metastasis samples from 419 colorectal cancer patients were examined for cancer-associated markers including serum MMP8, the pre- and postoperative high levels of MMP8 were associated with worse 10-year overall survival." (PMID 36677584, 2023). "Matrix metalloproteinase-8 (MMP-8) is a gene associated with inflammation and prognosis in colorectal cancer (CRC)." (PMID 33052136, 2020). "Logistic regression analysis of associations between MMP-8 rs11225395 polymorphism and risk of colorectal cancer." (PMID 33052136, 2020). "The associations between MMP-8 rs11225395 polymorphism and clinical characteristics of colorectal cancer." (PMID 33052136, 2020). "In a study with 148 colorectal cancer patients, high serum MMP-8 and TIMP-1 associated with advanced stage." (PMID 29929486, 2018). "Recently, high‐serum MMP‐8 levels were associated with systemic inflammation and adverse outcome in colorectal cancer (CRC) and it was suggested that serum MMP‐8 could therefore be a pertinent additional prognostic parameter in CRC." (PMID 34800007, 2022). "Stratified analyses between MMP-8 rs11225395 polymorphism and the risk of colorectal cancer." (PMID 33052136, 2020). "However, in ovarian cancer, the overexpression of MMP-8 could promote the invasive potential of cancer, and in both hepatocellular carcinoma and colorectal cancer, higher MMP-8 serum levels have been reported to be associated with significantly worse survival." (PMID 31590330, 2019). "In colorectal cancer, correlation between the step-wise increase of MMP8 levels and tumor malignancy was found." (PMID 31514474, 2019). "In colorectal cancer patients, increased serum MMP8 levels were measured compared to healthy controls and a high MMP8 level correlated with malignancy, reduced survival and increased systemic inflammation." (PMID 31514474, 2019). "In colorectal cancer, we found that high levels of serum MMP-8 and TIMP-1 serve as prognostic factors." (PMID 29929486, 2018). "We have previously shown that serum MMP-8 levels increase in colorectal cancer (CRC) and correlate with distant metastasis." (PMID 29808017, 2018). "In colorectal cancer, high serum MMP-8 levels and high blood neutrophil and leukocyte count correlated positively, but correlations between TIMP-1 and white blood cell count were less clear." (PMID 29929486, 2018). "Moreover, MMP-8 expression is associated with improved survival of tongue cancer patients, even though MMP-8 serum levels correlate with colorectal cancer stage and distant metastases." (PMID 29747434, 2018). "Based on a molecular docking method, it also inhibits post-translational forms of MMP-8 and MMP-13 in colorectal cancer progression and significantly palliates colorectal cancer invasion and metastasis." (PMID 38611849, 2024). "In a study on colorectal cancer (CRC), elevated levels of MMP-8 were detected with increasing stage of cancer." (PMID 39917664, 2024). "The aim of our study was to investigate the prognostic roles of MMP-8, MMP-9, and TIMP-1 in colorectal cancer." (PMID 29929486, 2018). "Of median MMP-8, MMP-9, and TIMP-1 serum levels prior to surgery for colorectal cancer and for controls with benign disease, only TIMP-1 levels were higher in patients with CRC than in controls (P = 0.037, Mann-Whitney U-test)." (PMID 29929486, 2018). "Our aim is to investigate the prognostic role of MMP-8, − 9, and TIMP-1 in colorectal cancer (CRC) and their relationship to inflammation." (PMID 29929486, 2018). "All in all, MMP-8 and TIMP-1 seem to influence the prognosis of colorectal cancer patients to a greater extent than MMP-9 seems to do." (PMID 29929486, 2018). "In this study, we studied the prognostic value of MMP-2, MMP-8 and MMP-9 immunoexpression in colorectal cancer." (PMID 23216739, 2012).
colorectal cancer (continued). "We studied the prognostic value of immunohistochemical expression of MMP-2, MMP-8, and MMP-9 in a series of 619 colorectal cancer patients using tissue microarray specimens." (PMID 23216739, 2012). "In colorectal cancer (CRC), a link between serum MMP-8 and CRP levels has been reported." (PMID 35328734, 2022). "B. Detection of MMP8 and MMP9 in colorectal cancer cells with SREBP1 gene intervention." (PMID 31299935, 2019). "In previous studies, we investigated the roles of MMPs including MMP2, MMP7, MMP8, MMP9 and MMP13 in the mice colorectal cancer model tissue, and observed that MMP7, MMP8, MMP9 are more important in colorectal cancer invasion and migration, and that MMP7 is regulated by NF-κB pathway." (PMID 31299935, 2019). "Few studies concern the prognostic value of MMP-8, MMP-9, or TIMP-1 in colorectal cancer." (PMID 29929486, 2018). "Serum MMP-8 and TIMP-1 may serve as prognostic factors in colorectal cancer." (PMID 29929486, 2018).
Obesity (19 papers, 2013 to 2026). Accumulation of substantial excess body fat. "This study provides evidence for a protective effect of obesity in mechanically ventilated patients and highlights the potential role of MMP-8 level as a biomarker for predicting mortality risk in this population." (PMID 37464428, 2023). "Lower level of insulin-like growth factor-binding protein (IGFBP-1) has been observed in insulin resistance, while higher level of matrix metalloproteinase-8 (MMP-8) has been linked to obesity." (PMID 32923723, 2020). "MMP-8 levels were similarly increased in obesity and associated with insulin resistance." (PMID 38678254, 2024). "The results suggest that salivary adiponectin levels may be associated with obesity-induced changes in the periodontium, as they closely followed clinical indices of gingival disease, while the biochemical marker MMP8 was less decisive." (PMID 37047877, 2023). "In addition, sex, smoking, and obesity are associated with both MMP-8 and TIMP-1 concentrations." (PMID 39917664, 2024). "Moreover, there is preliminary evidence that lower serum concentrations IGFBP-1 and higher serum concentrations of MMP-8 may be linked to low-grade inflammation and obesity, providing initial evidence of use as metabolic markers as well." (PMID 33375174, 2020). "Together, these findings suggest obesity creates a pro-inflammatory state characterized by upregulation of MMPs like MMP-8 and MMP-9, potentially driven by increases in mediators like lipocalin-2." (PMID 38678254, 2024). "In the PPI network constructed based on these genes, LCN2, ELANE, and MMP8 processed the most nodes, indicating their key roles in the obesity-related immune network." (PMID 39609876, 2024). "Overweight and mild obesity is an independent protective factor, and MMP-8 is identified as a potential biomarker for predicting the outcomes in non-neoplastic condition." (PMID 37464428, 2023). "In a mouse model of blunt chest trauma, lean mice had significantly higher levels of MMP-8 in the first 6 h compared to obesity." (PMID 37464428, 2023). "A secondary aim was to evaluate the relationships of IGFBP-1 and MMP-8 with the degree of obesity as well as the dietary intake of energy yielding nutrients, vitamins and minerals." (PMID 32923723, 2020). "Additionally, a significant positive association was found for MMP-8 and smoking, CRP, and an inverse association with obesity and fasting time." (PMID 39917664, 2024). "However, there is a paper evaluating serum MMP-8 levels in relation to skeletal characteristics among children and adolescents with obesity." (PMID 38138968, 2023). "The ELISA kit was used to measure the MMP8 levels to determine potential markers for obesity." (PMID 37047877, 2023). "However, when studying the association between MMP-8, TIMP-1 and disease outcomes, statistical models must be carefully adjusted for age, gender, smoking and obesity, as they seem to be major determinants of the systemic concentration of this enzyme and its inhibitor." (PMID 39917664, 2024). "Finally, our study, conducted from a clinical perspective, has revealed a correlation between MMP-8 and BMI, suggesting that MMP-8 may be a potential underlying cause of the obesity paradox." (PMID 37464428, 2023). "However, a contradictory finding has been reported in a twin cohort on obesity and MMP-8 levels, where MMP-8 concentration and the MMP-8/TIMP-1 molar ratio increased with increasing weight." (PMID 39917664, 2024). "Therefore, in this study, the elevated expression of upregulated DEGs enriched in serine metabolism, such as ELANE, CTSG, and MMP8, could result in increased serine hydrolysis and a subsequent reduction in serine levels within the body, thereby contributing to the onset and development of obesity." (PMID 39609876, 2024). "The mechanism by which MMP-8 is related to obesity and insulin resistance is not completely clarified." (PMID 33375174, 2020).
Obesity (continued). "Descriptive statistics of all study participant saliva samples tested for Bone Panel (osteoprotegrin (OPG), leptin, parathyroid hormone (PTH) and insulin), Matrix Metalloproteinase Panel (MMP-2, MMP-8, MMP-9) and Obesity Panel (adiponectin and C-reactive protein (CRP))." (PMID 23577067, 2013). "Descriptive statistics of all study participant serum samples tested for Bone Panel (osteoprotegrin (OPG), leptin, parathyroid hormone (PTH) and insulin), Matrix Metalloproteinase Panel (MMP-2, MMP-8, MMP-9) and Obesity Panel (adiponectin and C-reactive protein (CRP))." (PMID 23577067, 2013). "In addition, the extent to which IGFBP-1 and MMP-8 may be modified by dietary intake has not been studied, although a link with human nutritional status, like obesity, has been reported." (PMID 32923723, 2020).